ITPR2 (inositol 1,4,5-trisphosphate receptor type 2)
Diseases named in the same sentence as ITPR2 in open-access papers (continued):
Sharing a sentence is not in itself a finding about the gene and the disease.
tumor (18 papers, 2009 to 2025). "Recent genome-wide association studies have implicated the ITPR2 gene represents a novel risk locus for renal cell carcinoma, while miR-145 is considered a tumour suppressor being downregulated in several tumour types." (PMID 35163550, 2022). "Our study establishes a Tumor Microenvironment-derived Prognostic Model (MPM) that integrates eight TME-associated genes (CXCL12, GZMB, ITPR2, LYN, RAB9B, RGMB, RUFY4, TRIM16) to stratify AML patients into distinct risk categories with significant survival differences." (PMID 40608798, 2025). "One possible explanation is that the ITPR2 gene could be blocked by other miRNAs in the tumor cells." (PMID 26694163, 2015). "These transformation-encoding CNAs, together with deletion of TNF on 6p, and amplification of RAD51AP1 and ITPR2 on 12p, are correlated with a suppression of cell cycle arrest, senescence, and apoptosis, i.e., a tumor cell’s immortality, and a patient’s shorter survival time." (PMID 25875127, 2015). "Out of these, we have chosen three most changed in LSCCs namely RGS5 (fold change 0.08), MAF (fold change 0.15), and ITPR2 (fold change 0.3) which are attractive candidates for novel tumor suppressors according to their function and involvement in other cancers." (PMID 26694163, 2015). "The expressions of ITPR2, MDM2, KRAS and CDK4 were also highest in the CLDN2+ AT2 cells, and higher in the tumor-derived CLDN2+ AT2 cells than the normal ones." (PMID 37488117, 2023). "Interestingly, MC5 (PIK3R1, ITPR2, LRP2) was mainly seen in pre-treatment tumor cells of positive immune state change group." (PMID 38714665, 2024). "As a result, we found that ITPR1, ITPR2, and ITPR3 proteins may interact with tumor-promoting genes, such as PLCB1, PLCB2, PRKCA, and RGS21, which may partially explain its oncogene roles." (PMID 35580861, 2022). "To verify if the observed downregulation of MAF, ITPR2 and RGS5 was characteristic also for primary LSCC specimens, we analyzed group of 22 tumors and five no tumor controls by quantitative real time PCR." (PMID 26694163, 2015). "Moreover, by combining mRNA expression microarray data for the group of LSCC cell lines and no-tumor controls with public available miRNA target databases we indicated potential miR-1290 target genes downregulated in LSCC namely MAF and ITPR2." (PMID 26694163, 2015).
cancer (13 papers, 2013 to 2025). A tumor composed of atypical neoplastic, often pleomorphic cells that invade other tissues. "The involvement of MAF and ITPR2 in the regulation of apoptosis and radioresistance reflects therefore well the role of miR-1290 reported in other cancers." (PMID 26694163, 2015). "In addition to ITPR2, EGFR is frequently mutated or overexpressed in various cancer types, and in PDAC particularly, EGFR is essential for KRAS-driven pancreatic carcinogenesis." (PMID 32629766, 2020). "Emerging evidence has indicated that ITPR1, ITPR2, and ITPR3 were universally dysregulated in many cancers." (PMID 35580861, 2022). "miR-145-5p has been found to suppress cancer cell proliferation, invasion, stemness, chemotherapy, and radiation sensitivity in patients with PCa by targeting different regulators such as DNMT3a, TWIST1, ITPR2, AR, and NMT3b." (PMID 35368699, 2022).
psychiatric disorder (1 paper, 2024). A disorder characterized by behavioral and/or psychological abnormalities, often accompanied by physical symptoms. "Together, the findings reveal novel insights for calcium homeostasis in manipulating developmental transition from OPCs to pre‐OLs; additionally, the involvement of OLs‐originated ITPR2 in depressive behaviors provides new therapeutic strategies to alleviate myelin‐associated psychiatric disorders." (PMID 38476116, 2024).
ITPR2 also shares sentences with these, for which no sentence is quoted: diabetes (7 papers); breast carcinoma (5); liver cancer (5); cardiomyopathy (3); Cognitive impairment (3); myocardial infarction (3); Alzheimer disease (2); atrial fibrillation (2); cardiac hypertrophy (2); clear cell renal cell carcinoma (2); diffuse large B-cell lymphoma (2); ischemia (2); Stroke (2); Type 2 diabetes (2); adenocarcinoma (1); Alexander disease (1); alopecia (1); amyotrophic lateral sclerosis (1); atherosclerosis (1); autism (1); autism spectrum disorder (1); B-cell lymphoma (1); bone disorder (1); brain disorder (1); brain tumor (1); breast tumors (1); cardiac arrhythmias (1); cardiac ischemia (1); chronic kidney disease (1); chronic lymphocytic leukemia (1).
A further 39 diseases each share a sentence with ITPR2 in 1 paper.